SNORA25B (small nucleolar RNA, H/ACA box 25B)
Gene: Small nucleolar RNA gene on chromosome 7 (115,581,315 to 115,581,442, reverse strand). Ensembl gene ENSG00000202377.
Gene Ontology:
Biological process: RNA processing
Cellular component: nucleolus
Homologues: Orthologues: macaque SNORA25B (94% identical), mouse Gm55085 (59% identical). Paralogues in human: SNORA25 (87% identical).